ANK1 (ankyrin 1)
Diseases named in the same sentence as ANK1 in open-access papers (continued):
Sharing a sentence is not in itself a finding about the gene and the disease.
cancer (16 papers, 2014 to 2024). A tumor composed of atypical neoplastic, often pleomorphic cells that invade other tissues. "DNA hypermethylation at multiple ANK1 CGI promoter regions is associated with cancer-linked changes in miRNA levels." (PMID 38390894, 2024). "There might be cancer-associated hypomethylation of this ANK1 promoter, which could influence miR-486 levels as well as ANK1 isoform abundance ratios." (PMID 38390894, 2024). "Few genes are located near these regions and only a small subset are transcriptionally deregulated in GSC including ANK1, a gene known to maintain cell morphology and promote cancer cell growth." (PMID 29587824, 2018). "The MSigDB Cancer Neighborhood highlighted cancer-associated genes, TAL1, ANK1, SPTB, SPTA1, PRDX2, MAP2K3, etc.." (PMID 25522020, 2014). "High expression of ANK1 and FGFR1 are associated with poor outcomes in several cancer types." (PMID 37182141, 2023). "Based on these studiesand our findings, environmental risk factors, such as betel quid and cigarette, induced epigenetic repression of ANK1 and miR-486-3p may play important role inoral cancer development." (PMID 31253192, 2019). "Since we have demonstrated ANK1 plays a role in cell motility following DNA damage, we hypothesised that high levels of ANK1 could accelerate the metastasis of cancer cells that are resistant to chemotherapy." (PMID 27054339, 2016). "Importantly, we found that higher ANK1 expression correlates with decreased survival in cancer patients." (PMID 27054339, 2016). "In light of the role ANK1 plays in cell motility post-DNA damage, we postulate that high levels of ANK1 could accelerate the metastasis of cancer cells that are resistant to chemotherapy." (PMID 27054339, 2016). "Importantly, we found that high ANK1 levels correlate with reduced survival in cancer patients." (PMID 27054339, 2016). "Since ANK1 has not been previously shown to be aberrantly methylated in cancer, we further examined the methylation of ANK1." (PMID 27144336, 2016). "Among Cancer Gene Census genes, 1346 events were detected in 947 different loci, with the most recurrent ones being those in CLTCL1 (24 cases), CSMD3 (21 cases), MYH9 (20 cases), ANK1 (19 cases), TPR (19 cases), MYH11 (18 cases), PTPN13 (18 cases), and POLQ (17 cases)." (PMID 33809641, 2021). "There was a significant association between overexpression of ankyrin-1 and reduced survival, using univariate analysis (p=0.026), with a median survival of 14.7 months in the ankyrin-1-overexpressing cases versus 22.6 months in patients without ankyrin-1- overexpressing cancers." (PMID 27144336, 2016).
tumor (12 papers, 2016 to 2025). "During the evolution of tumor cells, driver mutation occurred in a large number of oncogenic genes, including Smarca4, Cxcr4, Ctnnd2 and Ank1." (PMID 36424557, 2022). "The malignant mutation event was localized to the tumor cell clusters with shared mutation of ANK1 and IFITM2 in all malignant subpopulations of all MM patients." (PMID 36131282, 2022). "We noticed a positive correlation between TRPA1 and ANK1, a membrane-associated cytoskeletal protein, in GBM, KICH, KIRC, LUSC, READ and THYM tumours." (PMID 39770499, 2024). "miRNA-486-5p is a tumor suppressor miRNA that is often downregulated, and which correlated with ankyrin 1 (ANK1) expression in NSCLC." (PMID 29723992, 2018). "Tumor-associated reductions in SPTB were associated with similar reductions in SPTA1 (70%), SLC4A1 (60%), and ANK1 (70%) in tumor tissue when compared to control tissue." (PMID 27799870, 2016). "Additionally, the two tumor-metastatic markers, ANK1 and GYPA, were also identified as downregulated in SCLC patients." (PMID 34996345, 2022). "Importantly, we found that higher ANK1 levels alone correlated with lower tumour-free patient survival in the clinical setting." (PMID 27054339, 2016). "Also, the tumorigenicity of ANK1-KO-AsPC1 cells was remarkably suppressed in athymic nude mice compared to control cells (p<0.005) with reduced tumor volumes apparent within one week of transplantation (p=0.00029)." (PMID 27144336, 2016). "This suggests that ANK1 expression might potentially be used as a prognostic marker in patients with specific tumours." (PMID 27054339, 2016). "The poor outcome of the subclonal ANK1 mutation may be caused by upregulation of IL4I1, IDO1, IFNG and MAPK12 which showed potential roles in tumor immune evasion through accumulation of immunosuppressive cells such as regulatory T cells and myeloid derived suppressor cells." (PMID 35962343, 2022). "Subclonal ANK1 mutation is related to adverse outcomes of CRC through increasing IL4I1, IDO1, IFNG and MAPK12, which may cause tumor immune escape through the accumulation of immunosuppressive cells such as regulatory T cells and myeloid derived suppressive cells." (PMID 35962343, 2022). "We also found that ANK1 (P = 0.0018), IL4I1 (P = 1.2e−12), IDO1 (P = 0), IFNG (P = 0)and MAPK12 (P = 2.2e−12) are positively correlated with PD-L1 expression in CRC cancer which has been reported to be associated with worse prognosis and counteract effect of tumor-infiltrating lymphocytes." (PMID 35962343, 2022). "A previous study demonstrated that circFOKX2 not only interacts with YBX1 and hnRNPK to elevate the expression of the oncogenes NUF2 and PDXK but also functions as a sponge for miR-942 to upregulate the expression of ANK1, GDNF, and PAX6, which contribute to tumor progression in PDAC." (PMID 34419070, 2021).
infection (11 papers, 2012 to 2025). The state of being infected such as from the introduction of a foreign agent such as serum, vaccine, antigenic substance or organism. "Upon further examination, the Ank-1(MRI96570) mutation was found to inhibit intraerythrocytic parasite maturation, whereas Ank-1(MRI95845) caused increased bystander erythrocyte clearance during infection." (PMID 28751503, 2017). "We measured the TUNEL-positivity of P. chabaudi in Ank-1(MRI61689/+) erythrocytes during the late trophozoite stage of the infections, which was the portion of the parasite lifecycle affected by the Ank1 mutation in the Ank-1(MRI23420/+) line." (PMID 27848995, 2016). "Of particular interest was the intermediate susceptibility of Ank1+/Ity16 mice to infection with Salmonella Typhimurium." (PMID 23390527, 2013). "Ank1+/Ity16 heterozygous mice present an intermediate phenotype with respect to susceptibility to infection (survival) when compared to Ank1+/+ and Ank1Ity16/Ity16 littermates." (PMID 23390527, 2013). "To understand the pathophysiology of the underlying susceptibility of Ank1+/Ity16 mice, we followed the animals for a longer period of time during infection." (PMID 23390527, 2013). "Given that O. tsutsugamushi expresses ank1 and ank6 throughout infection of host cells, we assessed if the pathogen lowers RIPK3 levels." (PMID 40430799, 2025). "Specifically, O. tsutsugamushi employs Ank1 and Ank6 to inhibit accumulation of nuclear factor kappa-light-chain-enhancer of active B cells (NF-κB) and NF-κB-dependent transcription during infection." (PMID 37256108, 2023). "Although the Ank-1(MRI95845/MRI95845) erythrocytes were more rapidly cleared from circulation during an infection, an impairment in intraerythrocytic parasite maturation was observed in the infected Ank-1(MRI96570/+) erythrocytes." (PMID 28751503, 2017). "Uninfected Ank-1(MRI61689/+) erythrocytes were also more likely to be cleared from circulation during infection; the “bystander effect”." (PMID 27848995, 2016). "During infection, iron accumulated in the kidneys of Ank1+/Ity16 mice where bacterial loads were high compared to littermate controls." (PMID 23390527, 2013). "On the other hand, the liver and kidney expression of the membrane iron exporter, Slc40a1 and Hmox1 was significantly higher in Ank1Ity16/Ity16 mice at day 0 and day 2 post infection compared to Ank1+/+." (PMID 23390527, 2013). "Early during infection (day 2), Ank1+/Ity16 mice behaved as wild type littermates for most subphenotypes we have measured including different blood parameters and organ CFUs." (PMID 23390527, 2013). "Low levels of Hamp expression in Ank1+/Ity16 heterozygous mice at the time of infection appears to contribute to iron accumulation in the kidney and liver and consequently favor bacterial growth." (PMID 23390527, 2013). "At day 6 post infection when the animals become clinically diseased, Ank1+/Ity16 mice presented consistent increase in bacterial load in the spleen, liver and kidney with a significant difference detected in the kidney." (PMID 23390527, 2013). "We do not know at the moment the exact mechanism of how hepcidin is improving resistance to infection in Ank1+/Ity16 heterozygous mice." (PMID 23390527, 2013). "We first verified that O. tsutsugamushi expresses ank1 and ank6 throughout infection of HeLa cells." (PMID 39976440, 2025). "The higher red cell mass present in Ank1+/Ity16 heterozygous mice during infection could be explained by increased Epo expression by the kidneys." (PMID 23390527, 2013). "Finally, the infected Ank-1(MRI61689/+) erythrocytes might more prone to destruction during the course of infection (increased clearance), thus posing a challenge for the parasite to establish a successful infection." (PMID 27848995, 2016).
infection (continued). "These two mouse lines, Ank-1(MRI96570/+) and Ank-1(MRI95845/MRI95845), displayed hematological and clinical features consistent with HS, and a marked resistance to infection by the murine malarial parasite, Plasmodium chabaudi." (PMID 28751503, 2017). "The Ank-1(MRI61689/+) RBCs were also more likely to be cleared from circulation during infection, an observation independent of number of parasitized erythrocytes." (PMID 27848995, 2016). "In addition, Ank-1(MRI61689/+) have a significantly increased survival rate, where all the Ank-1(MRI61689/+) mice survived the infection compared to the 16% survival of wild-type mice." (PMID 27848995, 2016). "At day 6 post infection, iron pigment deposition was detected in the liver and kidneys of Ank1+/Ity16 mice and not in wild type littermates." (PMID 23390527, 2013). "At the infection dose of 100 tachyzoites per mouse, the parental strain ME49 killed all the mice, whereas both ANK1 and DnaK-TPR single deletion mutants killed about 70% of infected mice, suggesting that the virulence of both ANK1 and DnaK-TPR mutants was slightly attenuated in laboratory mice." (PMID 29180989, 2017). "However, mutants lacking ANK1 or DnaK-TPR displayed modest virulence attenuation during mice infection." (PMID 29180989, 2017). "During infection, liver Hamp expression levels were not significantly modulated in both wild-type mice and Ank1+/Ity16 heterozygous mice although we did observe a modest but significant increase in kidney Hamp expression in Ank1+/Ity16 mice later during infection." (PMID 23390527, 2013).
adenocarcinoma (3 papers, 2016 to 2022). A common cancer characterized by the presence of malignant glandular cells. "Aberrant methylation of the CGI covering the TSS of ANK1 variant 9 (termed ANK1B promoter) repressed both ANK1 and miR-486-5p, and was specific for adenocarcinoma." (PMID 35172717, 2022).
neurodegenerative disease (3 papers, 2020 to 2025). A disorder of the central nervous system characterized by gradual and progressive loss of neural tissue and neurologic function. "Neurodegenerative disease-specific differential DNA methylation has also been reported for ANK1." (PMID 32991610, 2020).
genetic disorder (1 paper, 2025). "HS is a genetic disorder affecting erythrocyte membrane proteins, most commonly ankyrin-1, band 3, β-spectrin, α-spectrin, and Protein 4.2." (PMID 41007072, 2025).
inflammation (1 paper, 2019). Aberrant reaction of the microcirculation characterized by movement of fluid and leukocytes from the blood into extravascular tissues. "Transient receptor potential (TRP) vanilloid 1 (TRPV1) and ankyrin 1 (TRPA1) both may play important roles in lung inflammation and AHR." (PMID 31281589, 2019).
psychiatric disease (1 paper, 2021). "Thus, dysregulation of ANK1, leading to reduced AnkR, Kv3.1b, and PNN density, may be a common pathomechanism in neurological and psychiatric disease." (PMID 34180393, 2021).
retinopathy (1 paper, 2013). "Moreover, for any retinopathy, there were several nominally significant associations with SNPs close to the ANK1, SLC30A8, MTNR1B, TMPRSS6 and HK1 loci." (PMID 24244560, 2013). "An index SNP at the ANK1 locus also associated with CKD and retinopathy in non-diabetic individuals." (PMID 24244560, 2013).
ANK1 also shares sentences with these, for which no sentence is quoted: neurological disorders (3 papers); Ataxia (2); breast carcinoma (2); cardiac hypertrophy (2); depression (2); Jaundice (2); Parkinson’s (2); Achalasia (1); acute erythroleukemia (1); Alagille syndrome (1); Asperger syndrome (1); Cachexia (1); childhood asthma (1); cholestasis (1); coagulopathy (1); cognitive deficits (1); Congenital hemolytic anemia (1); dementia (1); dilated cardiomyopathy (1); Down syndrome (1); gallstones (1); haemolytic anaemia (1); hemoglobinopathies (1); idiopathic pulmonary fibrosis (1); Kallmann syndrome (1); leukocytosis (1); leukopenia (1); Lewy bodies Dementia (1); lung disease (1); lymph node metastasis (1).
A further 18 diseases each share a sentence with ANK1 in 1 paper.